ID1 (inhibitor of DNA binding 1)
Diseases named in the same sentence as ID1 in open-access papers (continued):
Sharing a sentence is not in itself a finding about the gene and the disease.
liver fibrosis (7 papers, 2014 to 2024). "The upregulated pathways in UHRF1-null adipocytes included those linked with pulmonary fibrosis, hepatic fibrosis, ID1 signaling, pulmonary healing pathway, signaling by Rho Family GTPase, and Bex2 signaling." (PMID 38789534, 2024). "Ursodeoxycholic acid (UDCA), for instance, can alleviate liver fibrosis by promoting liver regeneration through the activation of the ID1-Wnt Family Member 2 (WNT2)/hepatocyte growth factor (HGF) pathway." (PMID 39199400, 2024). "Regarding liver fibrosis, BMP9 has the potential to induce its progression through the activation of the ALK1–Smad1/5 signaling pathway and associated targets such as ID1, Hepcidin and Snail." (PMID 39199400, 2024). "Given that the BMP9 receptors ALK1 and Endoglin, as well as the BMP9 downstream targets Hepcidin and ID1, have significant roles in liver fibrosis, we will comprehensively discuss each of these components individually." (PMID 39199400, 2024). "The top 30 DEGs involved in the occurrence of liver fibrosis were selected and displayed as the heat map, which revealed that ID1 expression was markedly decreased in CCl4-treated Smad4Δhep mice compared with that in Smad4fl/fl mice." (PMID 36232998, 2022). "Our results showed that Smad4 deletion in hepatocytes decreased CCl4-induced liver fibrosis by regulating the expression of inhibitor of differentiation 1 (ID1) and the secretion of connective tissue growth factor (CTGF) in hepatocytes." (PMID 36232998, 2022). "Based on the verified correlation between ID1 and TGF-β in LX2 cells, we further detected the expression of ID1 in the liver fibrosis mouse model." (PMID 34772443, 2021). "An Id1 knockdown mouse model was also used to assess the role of Id1 in UDCA alleviation of liver fibrosis." (PMID 33635004, 2021). "Considering the important role of regeneration in the treatment of liver fibrosis, and upregulation of the Id1 gene in BDL mice after UDCA treatment, we examined the impact of UDCA treatment on liver regeneration in the PH model." (PMID 33635004, 2021). "ID1 has been identified as a potential target for therapeutic interventions of liver fibrosis." (PMID 39199400, 2024). "Collectively, these results indicated that Smad4 deficiency in hepatocytes decreased the expression of ID1 and CTGF, which may be involved in the process of liver fibrosis." (PMID 36232998, 2022). "Because of its proregeneration effects, upregulation of the Id1 gene may be beneficial for liver fibrosis." (PMID 33635004, 2021). "UDCA alleviates liver fibrosis and increased Id1 mRNA expression in BDL mice model." (PMID 33635004, 2021). "Moreover, UCB-Exo treatment can mitigate liver fibrosis through inhibition of the TGF-β/ID1 signaling pathway." (PMID 34772443, 2021). "The molecular mechanisms that underlie the effects of the Id1 protein on HSC activation and liver fibrosis remain unclear." (PMID 25393508, 2014). "This indicates that ID1 may be a protective factor for liver fibrosis." (PMID 39199400, 2024). "In this study, we found that the expression of ID1 and CTGF in hepatocytes was markedly downregulated in hepatocyte-specific Smad4 deletion mice with liver fibrosis." (PMID 36232998, 2022). "During liver fibrosis, ligand-activated ALK1 activates the target gene Id1 through the Smad1 pathway, thereby inducing HSCs to differentiate into fibroblasts, which produce ECM proteins." (PMID 25393508, 2014). "This review summarizes the indirect connection between BMP9 and liver fibrosis, with a focus on the BMP9 signaling pathway members ALK1, endoglin, Id1, hepcidin and Snail." (PMID 25393508, 2014). "In a CCl4-induced liver fibrosis model, the deletion of Smad4 in hepatocytes resulted in suppressed ID1 expression and connective tissue growth factor (CTGF) secretion, subsequently activating the p38 and p65 signaling pathways in HSCs and thereby alleviating liver fibrosis." (PMID 39199400, 2024).
liver fibrosis (continued). "Besides ID1, TGF-β1 also promotes the activities of several signaling pathways including Smad2/3, TAK1, JNK, p38, MAPKs, RhoA–ROCK, JAK–STAT3, and PI3K–AKT, which contribute to the induction of hepatic fibrosis." (PMID 39199400, 2024). "Molecularly, Smad4 expression in hepatocytes upregulated the expression of ID1 and further enhanced the paracrine activity of CTGF; subsequently, mediated by EGFR, CTGF promoted HSCs’ activation by regulating the p38 and p65 signaling pathways, which in turn led to liver fibrosis." (PMID 36232998, 2022). "Therefore, we speculated that ID1 and CTGF might play important roles in liver fibrosis of Smad4Δhep mice and Smad4fl/fl mice." (PMID 36232998, 2022).
oral squamous cell carcinoma (7 papers, 2012 to 2024). "Correlation between the expression of Id-1 and hyperthermia-associated molecules in oral squamous cell carcinoma." (PMID 33710819, 2021). "Moreover, the induction of SERPINE1 and ID1 on proliferation is validated in oral squamous cell carcinoma and normal cutaneous keratinocytes." (PMID 38786031, 2024). "Id1 and NF-κB are highly expressed in oral squamous cell carcinoma (OSCC)." (PMID 24572994, 2014). "Oral squamous cell carcinoma cells transfected with miR-100 may modify the expression of a number of oncogenes including ID1, EGR2, MMP13, and FGFR3." (PMID 23173870, 2012). "The oral squamous cell carcinoma cell HSC2, when exposed to milk, increased ID1 and ID3 genes but failed to increase IL11 (data not shown)." (PMID 34789212, 2021).
rheumatoid arthritis (7 papers, 2005 to 2021). A chronic, systemic autoimmune disorder characterized by inflammation in the synovial membranes and articular surfaces. "ID1 production in rheumatoid arthritis synovial fibroblasts is mostly contained within exosomes, which could be affected by endothelial progenitor cells, leading to JNK signaling pathway activation in human dermal microvascular endothelial cells." (PMID 34122424, 2021). "Moreover, BMP-6 has been suggested to play a role in rheumatoid arthritis (RA) and elevated levels of Id1 and Id3 have been found in the synovia of RA-patients." (PMID 15877825, 2005). "Sources of Id1 production in rheumatoid arthritis synovial tissue (RA ST) and its range of functional effects in RA remain to be clarified." (PMID 27071670, 2016). "The upregulation of ID1 and ID3 genes has been reported in patients with rheumatoid arthritis (RA)." (PMID 28785583, 2017). "In addition, we should notice that an inhibitor of DNA binding 1 (ID1) protein was determined as a basic helix-loop-helix (bHLH)-ZIP transcription factor and also allowed to be secreted only in the synovial fluid, but not the blood plasma, of model animals with rheumatoid arthritis." (PMID 30261697, 2018).
triple-negative breast carcinoma (7 papers, 2013 to 2025). An invasive breast carcinoma which is negative for expression of estrogen receptor (ER), progesterone receptor (PR), and human epidermal growth factor receptor 2 (HER2). "To address the function of Id1 expressing cells within tumors, we developed independent murine models of Triple Negative Breast Cancer (TNBC) in which a genetic reporter permitted the prospective isolation of Id1+ cells." (PMID 32766238, 2020). "A decrease in ID1 and ID3 protein levels was also observed in a PDX cell line (IBT) generated from a patient with triple-negative breast cancer (TNBC)." (PMID 34031428, 2021). "The basic helix-loop-helix (bHLH) transcription factors inhibitor of differentiation 1 (Id1) and inhibitor of differentiation 3 (Id3) (referred to as Id) have an important role in maintaining the cancer stem cell (CSC) phenotype in the triple-negative breast cancer (TNBC) subtype." (PMID 32911668, 2020).
lymph node metastasis (6 papers, 2008 to 2024). "The results showed that the ID1 mRNA expression in bone marrow and peripheral blood was significantly associated with lymph node metastasis and peritoneal dissemination." (PMID 19491902, 2009). "In this study, the ID1 mRNA expression in bone marrow and peripheral blood was significantly associated with lymph node metastasis and peritoneal dissemination." (PMID 19491902, 2009). "Importantly, we revealed that high expression level of Id-1 is closely associated with tumor size, high stage, lymph node metastasis, and as an independent risk factor to predict overall survival." (PMID 29233161, 2017). "The expression of ID1 mRNA in bone marrow and peripheral blood was significantly associated with lymph node metastasis and peritoneal dissemination, and therefore constitutes a predictable marker for lymph node metastasis and peritoneal dissemination." (PMID 19491902, 2009). "In both bone marrow and peripheral blood samples, ID1 mRNA expression in the metastatic group was significantly higher than in any other group (P=0.003, P=0.0001, respectively) and significantly associated with lymph node metastasis and peritoneal dissemination." (PMID 19491902, 2009). "ID1 is highly expressed in TAMs of CRC patients with lymph node metastasis and positively correlated with CRC histologic grades and advanced TNM stages." (PMID 37996458, 2023). "They reported that Id-1 expression was higher when Dukes' stage increased and when there was a lymph node metastasis." (PMID 19014499, 2008). "Zhou and colleagues recently evaluated the prognostic relevance of the ID family by using a set of public databases and reported that higher mRNA levels of ID1 and ID4 were associated with lower histological grades, less lymph-node metastasis, and longer survival rates." (PMID 33514024, 2021). "Especially, in patients with evidence of lymphatic invasion, lymph node metastasis or peritoneal dissemination, we found significantly higher expression of ID1 mRNA in bone marrow samples compared to patients without metastasis." (PMID 19491902, 2009). "Similarly, in peripheral blood samples, the cases with lymphatic invasion, lymph node metastasis or peritoneal dissemination had significantly higher expression of ID1 mRNA compared to patients without metastasis." (PMID 19491902, 2009).
brain tumor (5 papers, 2014 to 2022). "However, deletion of ID1 in mouse brain tumors had only modest effects on animal survival, although CSCs of ID1 mutants have reduced self-renewal capacity in vitro." (PMID 30279357, 2018). "Brain tumors derived from LN229/COX-2 and LN229/Id1 cells were visibly larger than those derived from corresponding control cells harvested at the same time point." (PMID 24659686, 2014).
metastatic tumors (5 papers, 2014 to 2025). "Low levels of GCIP expression significantly correlated with high levels of Id1 expression in the metastatic tumors." (PMID 24970809, 2014). "In addition, ID1 expression was significantly higher in metastatic tumors at both N0 and N1 stages, indicating a potential role in tumor metastasis." (PMID 40919143, 2025). "In metastatic tumor cells, ID1 and ID3 facilitate the mesenchymal-to-epithelial conversion required for macro-metastatic disease progression, likely through antagonism of the bHLH protein Twist47." (PMID 34031428, 2021).
thyroid cancer (5 papers, 2014 to 2024). "With regard to the association between Id1 level and overall survival or disease free survival for thyroid cancer patients needs to be further studied." (PMID 32410828, 2020). "Several transcription factors (TFs) were under the control of Id1 in thyroid cancer including the basic Helix-Loop-Helix (bHLH) proteins DEC1 and DEC27." (PMID 30158530, 2018). "Recently we reported that the transcription regulator Id1 promotes aggressiveness of thyroid carcinomas by regulating the expression of genes involved in epithelial to mesenchymal transition (EMT), invasion, and migration." (PMID 30158530, 2018). "For example, ID1 regulates growth and differentiation in thyroid cancer cells, and ID3 was also identified as an early response protein and tumor marker for thyroid carcinomas." (PMID 24718460, 2014). "The repressed KLF17 promotes the motility and proliferation of human thyroid cancer TPC1 cells by altering the expression of zona occludens-1 (ZO-1) and Snai1, and activating the Akt pathway by upregulating inhibitor of DNA binding 1 (ID1)." (PMID 26662959, 2016). "However, the expression levels of ID1, ID3, and ID4 were downregulated in thyroid cancer." (PMID 38195969, 2024). "However, our observation that both these factors are strongly induced in Id1 over-expressing and highly aggressive thyroid cancer cells seems to indicate that DEC1 and DEC2 may be part of a transcriptional program that promotes aggressiveness and metastatic spreading of thyroid cancer." (PMID 30158530, 2018).
anemia (4 papers, 2016 to 2024). A reduction in the number of red blood cells, the amount of hemoglobin, and/or the volume of packed red blood cells. "The mice are unable to increase hepcidin and Id1 expression or to develop anemia in contrast to control mice." (PMID 30271947, 2018). "Paralleling Hamp1 expression, hepatic Id1 was not upregulated in early infection but was decreased as anemia became more severe, consistent with erythroid-mediated suppression of hepcidin (as a result of anemia) requiring a decrease in Smad signaling." (PMID 28893916, 2017). "Additionally, Id1 KO mice were found to display no anemia or splenomegaly (data not shown)." (PMID 27128622, 2016).
cardiomyopathy (4 papers, 2017 to 2024). A disease of the heart muscle or myocardium proper. "In cardiomyopathy, it has been reported that circ-Foxo3 interacts with anti-senescent proteins ID-1 and E2F1, as well as anti-stress proteins FAK and HIF1α, leading to the relocation of these proteins in cytoplasm." (PMID 38360615, 2024). "Meanwhile, circ-Foxo3 expression level is upregulated in aged patient and mice tissues, overexpression of circ-Foxo3 contributes to the progression of senescence in mice Dox-induced cardiomyopathy cells by interacting with ID1, E2F1, FAK, and HIF1A." (PMID 28219405, 2017).
Cirrhosis (4 papers, 2009 to 2022). A chronic disorder of the liver in which liver tissue becomes scarred and is partially replaced by regenerative nodules and fibrotic tissue resulting in loss of liver function. "Expression of Id1, 2, and 3 is increased during liver disease, with levels that escalate as liver disease progresses from hepatitis to cirrhosis." (PMID 19787063, 2009). "To further verify this result, we analyzed a public GEO dataset (GSE89377) and found that, compared to healthy individuals, the expression of ID1 and CTGF was dramatically increased in the liver tissues of patients with hepatitis and cirrhosis." (PMID 36232998, 2022). "As expected, we found that the expression of ID1 and CTGF was distinctly increased in patients with hepatitis and cirrhosis." (PMID 36232998, 2022). "Here, we verified the correlation between ID1, CTGF, hepatitis, and cirrhosis in clinical cases by analyzing the expression of ID1 and CTGF in 20 healthy individuals, 14 hepatitis patients, and 13 cirrhosis patients using the GEO dataset GSE89377." (PMID 36232998, 2022).
lymphoma (4 papers, 2008 to 2015). A malignant (clonal) proliferation of B- lymphocytes or T- lymphocytes which involves the lymph nodes, bone marrow and/or extranodal sites. "When both Hes1 and Id1 are expressed in thymocytes, lymphomas develop rapidly in all animals examined." (PMID 19688092, 2009). "We have also demonstrated that Hes1 expression acts synergistically with Id1 to promote lymphoma development." (PMID 19688092, 2009). "We have shown here that inhibition of E protein function by Id1 leads to apoptosis in a DP lymphoma cell line, and co-expression of Id1 with RORγt rescued cell death in these cells." (PMID 18489764, 2008). "Sensitivity to growth inhibition by TGF-β might depend on Smad1/5 signalling in lymphoma cell lines, which possibly initiates via Alk-5 and terminates in up-regulation of Id1 and other target genes." (PMID 21092277, 2010).
nasopharyngeal carcinoma (4 papers, 2014 to 2024). A carcinoma arising from the nasopharyngeal epithelium. "Up-regulation of Id1, together with the p65 subunit of NF-kB, has been proposed to be a marker for poor prognosis in nasopharyngeal carcinoma." (PMID 28122577, 2017). "In contrast, ectopic Id1 expression induces resistance to taxol treatment in breast, prostate and nasopharyngeal carcinoma cells." (PMID 28122577, 2017). "Similar situation is also observed in nasopharyngeal carcinoma, as shown in our recent study, Id1 and NF-κB subunit p65 in nasopharyngeal cancer are important factors for prediction of clinically poor outcomes." (PMID 24572994, 2014). "Likewise, in nasopharyngeal carcinoma, LMP1 induces an upregulation of Id-1 via FoxO3a inactivation." (PMID 30035100, 2018).
T cell lymphoma (4 papers, 2009 to 2025). "Both T cell-specific Id1 expression and Tcf3 ablation lead to T cell lymphoma formation in transgenic mice at high frequencies, while Id1 gene disruption can partially rescue the survival of Tcf3-null mice." (PMID 41146039, 2025). "We have previously shown that transgenic expression of Id1 under the control of the lck proximal promoter leads to the formation of T cell lymphoma in the thymus with high penetrance and a median survival of 21.5 weeks." (PMID 22393458, 2012). "In this report, we have examined Notch activities in a series of T cell lymphomas developed in Id1 transgenic mice in comparison to those in tumors from ROSA26-N1C/lck-Cre mice." (PMID 22393458, 2012). "Here, we made use of our collections of T cell lymphomas developed in mice expressing Id1 or Notch1 intracellular domain (N1C)." (PMID 22393458, 2012). "To test if these events occurred in Id1 transgenic T cell lymphomas, we determined levels of Notch1 transcripts by using PCR primers specific for exons 5–6 and exons 33–34 to amplify Notch1 transcripts via the 5′ and 3′ ends, respectively." (PMID 22393458, 2012). "For example, heterozygous Id1 transgenic mice, where T cell development is partially impaired, develop high incidence of T cell lymphoma." (PMID 19688092, 2009). "Subsequent in vitro assays prove that ID1 expression or E-protein inhibition directly stimulates NF-κB and its target cytokines, including tumor necrosis factor-α (TNF-α), in both DP T cell lymphoma cell line 16610D9 and thymocytes isolated from Id1 transgenic mice." (PMID 41146039, 2025). "Thus, Id1 plays an oncogenic role in developing T cell lymphoma in adult transgenic mice at a high frequency." (PMID 41146039, 2025). "Therefore, we made use of our collection of T cell lymphomas developed in transgenic mice expressing Id1, which like TAL1, inhibits E protein function." (PMID 22393458, 2012). "However, Hes1 promotes rapid tumorigenesis in a well-studied model of T-ALL in which expression of Id1 inhibits the function of E2A and HEB transcription factors, whose deficiency leads to T cell lymphoma." (PMID 19688092, 2009). "However, expression of Hes1 significantly shortens the latency of T cell lymphoma developed in Id1 transgenic mice, where the function of bHLH E proteins is inhibited." (PMID 19688092, 2009). "However, this may not be absolutely essential for lymphomagenesis in Id1 transgenic mice and additional factors could also cooperate with Id1 to induce T cell lymphoma." (PMID 22393458, 2012). "However, the onset of T cell lymphoma or tumor-free survival of Id1 transgenic mice does not appear to be proportional to the levels of Notch activities or depend on Notch activation." (PMID 22393458, 2012). "However, homozygous Id1 transgenic mice, in which T cell development is blocked at the DN1 stage, do not develop T cell lymphoma (data not shown)." (PMID 19688092, 2009).